ENSG00000251805
Synonyms: LOC124900541
Gene: Small Cajal body-specific RNA gene on chromosome 2 (24,273,614 to 24,273,741, reverse strand). Ensembl gene ENSG00000251805.
Gene Ontology:
Biological process: RNA processing
Cellular component: Cajal body; nucleolus